IL1B (interleukin 1 beta)
Diseases named in the same sentence as IL1B in open-access papers (continued):
Sharing a sentence is not in itself a finding about the gene and the disease.
migraine (continued). "Furthermore, plasma and cerebrospinal fluid levels of neuropeptides, histamine, proteases, and pro-inflammatory cytokines (e.g., TNFα, IL-1β) are elevated during migraine attacks, suggesting that neuroimmune interactions contribute to migraine pathogenesis." (PMID 35052756, 2021). "So, CGRP, TNF-α, and IL-1β were proposed as therapeutic targets of migraine." (PMID 33995549, 2021). "Additionally, proinflammatory cytokines, including IL-1β, IL-6, IL-8, and TNF-α have been implicated in migraine pain and are increased during migraine attacks." (PMID 32054443, 2020). "On the other hand, as mentioned, proinflammatory cytokines such as TNF-α, IL-1β and IL-6 could also affect nociceptive responses in the trigeminal pathway and play a role in migraine pain initiation." (PMID 32054443, 2020). "Cytokine Polymorphism (TNF-α and IL-1β gene polymorphisms) in patients with migraine without aura provide some more suggestive evidence for a possible contribution of inflammation in migraine." (PMID 30974836, 2019). "Based on accumulating evidence, IL-1β is involved in migraine pathology." (PMID 30971286, 2019). "The gain of function TNF-α-308 A and IL-1β + 3953 T allele gene polymorphisms are elevated in patients with migraine without aura, although the implications are unclear." (PMID 23181051, 2012). "Furthermore, enhanced expression of IL-1β was found in the meninges in an experimental animal model related to migraine." (PMID 21394197, 2011). "CGRP released by trigeminal ganglia neurons has been shown to function in a paracrine manner to activate trigeminal satellite glial cells to release various cytokines including IL-1β and nitric oxide, a molecule known to be involved in migraine pathophysiology." (PMID 21394197, 2011). "Among others, IL-1β and TNFα levels were elevated in jugular vein blood during migraine attacks." (PMID 21394197, 2011). "The shared pathways, such as those regulated by Il1b, Nox1, and Lcn2, are involved in both ferroptosis and immune responses, suggesting that targeting these pathways could modulate multiple aspects of the comorbid migraine and TMDs." (PMID 41465107, 2025). "Our results indicated that the effect of migraine in increasing the risk of AD development might be mediated by TNFα, while IL-1α, IL-1β, and IL-6 do not play a role in this process." (PMID 38903170, 2024). "However, saliva-based tests have indicated that IL-1β might be useful in identifying migraine, and IL-1β might be a potent cytokine in the pathogenesis of the inflammatory response in migraine." (PMID 37176049, 2023). "Saliva-based tests suggest that IL-1β might be useful in discriminating against migraine." (PMID 37176049, 2023). "Another study demonstrated that the expression of the NLRP3 inflammasome was upregulated in a migraine-relevant pain mouse model (that is pain was induced by recurrent NTG stimulation), shown by an increase in NLRP3 expression that was associated with IL-1β activation." (PMID 34112082, 2021). "It is found that the serum level of IL-1β is significantly increased among migraine patients compared with healthy controls and correlated positively with the level of calcitonin gene-related peptide (CGRP), a well-established neuropeptide implicated in migraine pathology." (PMID 33785039, 2021). "The serum level of IL‐1β, IL‐6, TNF‐α, and CGRP in the migraine group were significantly higher than the normal group." (PMID 41496770, 2025). "Pro-inflammatory cytokines – such as IL-1β, IL-6, IL-8, and TNF-α – are often elevated interictally in migraineurs compared to non-migraine controls." (PMID 41377228, 2025). "Proinflammatory cytokines, including IL-1β, IL-6, IL-8, and TNF-α, are elevated during migraine attacks, sensitizing nociceptive pathways such as the trigeminal system." (PMID 40175732, 2025). "A meta-analysis revealed that serum levels of CRP, IL-1β, IL-6, and TNF-α were elevated in migraine patients compared to healthy controls." (PMID 40149800, 2025).
migraine (continued). "Based on this review, IL-6, IL-1β, and TNF-α stand out as the most plausible biomarkers for migraine chronification." (PMID 41377228, 2025). "Pro-inflammatory cytokines, such as interleukin (IL)-1β, IL-6, and tumor necrosis factor (TNF)-α, rise during migraine attacks, sensitizing pain pathways and increasing gut permeability, worsening neuroinflammation." (PMID 40230722, 2025). "In a study, researchers found that in a mouse model of migraine induced by nitroglycerin, there was a significant increase in inflammatory factors such as TNF-α and IL-1β in the colon and a decrease in the integrity of the colonic epithelial barrier." (PMID 40143202, 2025). "A recent meta-analysis found significantly higher circulating levels of C-reactive protein (CRP), IL-1β, IL-6, and TNF-α in patients with migraine relative to healthy individuals." (PMID 41377228, 2025). "Activation of microglia has also been shown in migraine, in particular, in the trigeminal ganglion, microglia were activated by the introduction of NTG, which led to the release of IL-1β." (PMID 41515906, 2025). "Similar to our findings, previous studies indicated higher expression levels of proinflammatory cytokine genes or proteins (e.g., IL-1β, IL-6, and TNF-α) in the peripheral blood and trigeminovascular region of animals with NTG-induced migraine." (PMID 38612517, 2024). "In the ACC, the expression levels of IL-1β, IL-6, and TNF-α were higher in the NTG-induced migraine groups than in the VEH group; proinflammatory cytokine expression was significantly higher in the CM group than in the EM group." (PMID 38612517, 2024). "The results indicated increased expression of proinflammatory cytokines (IL-1β, IL-6, and TNF-α) in the Sp5C regions of NTG-induced migraine groups compared with the VEH group; expression levels were significantly higher in the EM group than in the CM group." (PMID 38612517, 2024). "The involvement of P2 × 7R in the headache process has already been reported, as P2 × 7R is involved in the migraine process by activating NLRP3 and thus releasing IL-1β during migraine development." (PMID 38573415, 2024). "included 10 studies with a total of 1842 participants, revealing significant elevations in serum CRP, IL-1β, IL-6, and TNF-ɑ levels among migraine patients, thus supporting the inflammation-related mechanisms proposed in this study." (PMID 39850553, 2024). "During migraine attacks, increased levels of pro-inflammatory cytokines such as TNF-α and IL-1β have been detected in the serum." (PMID 37755364, 2023). "Although the etiology of migraine is not fully understood, there is some evidence of increased levels of IL-1β and TNF-α in migraine and chronic tension-type headache." (PMID 35323721, 2022). "Meanwhile, previous studies have found that inflammation plays an important role in the pathophysiology of migraine, and the levels of serum inflammatory cytokines, such as CRP, IL-1β, IL-6, and TNF-α are higher in migraineurs compared with healthy controls." (PMID 35493816, 2022). "XZR reduced the degranulation of mast cells as well as the levels of CGRP, SP, NO, and proinflammatory cytokines, including TNF-α, IL-1β, and IL-6, suggesting that XZR improved migraine by relieving the neurogenic inflammatory response." (PMID 35928284, 2022). "Altered levels of pro-inflammation cytokines in plasma and serum, such as interleukin 1 beta (IL-1β), interleukin 6 (IL-6), and tumor necrosis factor alpha (TNF-α), has been demonstrated the correlation to migraine in both patients and animals." (PMID 35033010, 2022). "Levels of IL-1β, CCL3, CCL4, CXCL1, CCL22, and CCL8 were also measured in 55 healthy controls and 64 migraine patients." (PMID 34575163, 2021). "In summary, overexpression of miR‐34a‐5p inhibited the expression of SIRT1 and increased the expression or release of IL‐1β/COX2/PEG2, which further enhanced the release of CGRP, thereby triggering the pain during migraine onset." (PMID 33155431, 2021).
migraine (continued). "Because miR‐34a‐5p was shown to be up‐regulated in patients with migraine, we down‐regulated miR‐34a‐5p by using its inhibitor, and then we detected the expression level of SIRT1, IL‐1β, miR‐34a‐5p, NF‐κB p65 and COX2 by quantitative real‐time PCR." (PMID 33155431, 2021). "Based on clinical findings showing elevated IL-1β, and experimental findings involving IL-1β and both the peripheral trigeminal ganglion and central trigeminal vascular pathways, regulation of the Il-1β/IL-1 receptor type 1 axis might lead to new treatments for migraine." (PMID 34445635, 2021). "Proinflammatory cytokines such as IL-1β, IL-6, and TNF-α proved to have high concentrations in serum in patients with migraine, indicating that inflammation plays a significant role in migraine pathogenesis." (PMID 32516927, 2020). "These approaches have revealed a key contribution of NLRP3 to migraine, with MCC950, a specific NLRP3 antagonist, reducing periorbital and hind paw mechanical hypersensitivity and reversing increased expression of IL-1β in trigeminal ganglia." (PMID 32973552, 2020). "We evaluated the expression levels of NLRP3 and its downstream interleukin (IL)-1β protein in the trigeminal nucleus caudalis (TNC; which is a central area relevant to migraine pain) at different time points." (PMID 30971286, 2019). "The responsiveness of IL-1β to CGRP creates the potential for a positive feedback loop and, thus, a plurality of targets for therapeutic intervention in migraine." (PMID 19660121, 2009). "Preclinical research also shows that cytokines such as IL-1β and IL-6 can activate and sensitize meningeal and muscle nociceptors, suggesting their role in contributing to migraine pain." (PMID 40149800, 2025). "The combination of omega-3 fatty acids and nano-curcumin showed a significant decrease in the frequency of migraine attacks and serum level of IL-1β, while a non-significantdifferences was seen in the gene expression of IL-1β." (PMID 40005953, 2025). "Cytokine involvement in migraine has been extensively studied, particularly TNF-α and IL-1β." (PMID 40426647, 2025). "Both IL-1β and NLRP3 play crucial roles in the pathogenesis of migraine." (PMID 41441603, 2025). "Notably, combination nutraceutical therapies (e.g., omega-3 plus nano-curcumin) led to significant declines in IL-1β, IL-6, and TNF-α, along with fewer migraine attacks." (PMID 41377228, 2025). "Additionally, inflammatory markers such as interleukin (IL)-1β, IL-6, and tumor necrosis factor (TNF)-α have been observed to increase, particularly during migraine attack phases." (PMID 39698251, 2024). "Furthermore, according to available evidence, inflammatory factors such as interleukin (IL)‐1β, IL‐6, and tumor necrosis factor (TNF)‐α levels have also been shown to rise in patients with migraine, especially during migraine attack phases." (PMID 39055195, 2024). "Elevated levels of pro-inflammatory cytokines, such as interleukin-1 beta (IL-1β), interleukin-6 (IL-6), and tumor necrosis factor-alpha (TNF-α), have been observed in the blood and cerebrospinal fluid of individuals experiencing migraine attacks." (PMID 39107712, 2024). "Li Jinhong found that the levels of serum INF-α, IL-2, IL-17, IL-12P70, TNF-α, IL-5, IL-1β, and IL-4 were higher in adult migraine patients than in normal control group, which changed with different stages of the disease." (PMID 38356891, 2024). "Increased blood levels of IL1β and TNF have been reported in migraine patients." (PMID 39009958, 2024). "Migraine sufferers (with and without aura) and obese patients have elevated plasma or serum concentrations of many inflammatory markers, including IL-1β, IL-6, IL-8, TNF-α, and C-reactive protein levels." (PMID 39600744, 2024). "It found that IL-1β, IL-6, and TNF-α were all higher in patients with migraine than controls." (PMID 37016284, 2023).
migraine (continued). "Additionally, supporting a role for neurogenic inflammation in migraineurs, elevated levels of plasmatic IL-1β, prostaglandin E2, tumor necrosis factor-α (TNF-α), IL-6, or nitrite were observed during migraine attacks." (PMID 38062355, 2023). "In addition, pro-inflammatory cytokines such as interleukin (IL)-1β, IL-6, IL-8, and tumor necrosis factor-α (TNF-α) are increased during migraine attacks." (PMID 37755364, 2023). "Moreover, another recent study confirmed that the inflammatory cytokines, including IL-1β, TNF-α, and IL-6, significant decreased after EA treatment at GB20 and GB34 in a migraine model." (PMID 37190506, 2023). "Similarly, systemic deactivation of SFKs reduces cortical spreading depression (CSD), a migraine with aura model, and CSD-induced cerebral cortical inflammatory cytokines interleukin 1 beta (IL-1β) and tumor necrosis factor alpha (TNFα) gene expression." (PMID 36359895, 2022). "Proinflammatory cytokines, such as interleukin (IL)-1β, IL-6, and tumor necrosis factor-alpha (TNF-α), as well as anti-inflammatory cytokines, such as IL-10, are elevated in patients with migraine and are suggested to play a role in migraine." (PMID 36362765, 2022). "Pharmacological blocking NLRP3 or IL-1β with the NLRP3 antagonist MCC950 or IL-1ra not only improved NTG-induced hyperalgesia, but also inhibited the biomarkers related to central sensitization of migraine in TNC, such as p-ERK, c-Fos, and CGRP." (PMID 33785039, 2021). "The levels of IL-1β or chemokines were not dependent on the age of the individuals or the presence of migraine in patients with MD." (PMID 34575163, 2021). "Furthermore, serum concentrations of IL-1β, IL-6, IL-8, and TNF-α were found increased during migraine attacks." (PMID 34112082, 2021). "CO2-ZSE can effectively treat migraine, increase the expression of 5-HT, decrease the expression of NO, CGRP, and ET-1 to regulate vasomotor and inhibit the expression of NF-κBp65, IκBα, and IL-1β to alleviate neurogenic inflammation." (PMID 34916933, 2021). "Pro-inflammatory IL-1β plasma concentrations were higher in the sham-VNS group versus the verum nVNS, whereas anti-inflammatory cytokine IL-10 was elevated in migraine patients as compared to healthy subjects but was suppressed three months post-stimulation in both sham and VNS group." (PMID 31554241, 2019). "Despite the currently incomplete definition of the exact pathophysiology of migraine, cytokine-related genes, such as tumor necrosis factor (TNF), interleukin-1β (IL-1β) and IL-10, are known genetic candidates contributing to the predisposition towards migraine development." (PMID 24959879, 2014). "Indeed, migraine without aura attacks are seen in patients with cryopyrin-associated periodic syndromes (CAPS), where IL-1β is overproduced due to mutations in the NLRP3 inflammasome." (PMID 39080518, 2024). "Parenchymal IL-1β production could also play a significant role by triggering meningeal nociceptor activation in migraine without aura (i.e. without CSD)." (PMID 39080518, 2024). "BoNT/A may have a therapeutic function in migraines by reducing the expression of NLRP3 and IL-1β." (PMID 38836002, 2024). "Similarly, adults with MA have been found to exhibit higher plasma levels of IL-1β during headache-free periods and early stages of attacks as compared to those suffering from migraine without aura (MO)." (PMID 37755358, 2023). "Thus, regulation of the IL-1β cascade by anakinra and MCC950 may lead to new therapeutic options for migraine." (PMID 34445635, 2021). "Various vasoactive peptides (e.g., CGRP, PACAP, and substance P (SP)) and inflammatory mediators (e.g., nitric oxide (NO), IL-1β, and TNF-α) which are proposed to be involved in migraine pathogenesis, could impose their effects mainly through inducing neuroinflammation induction in the CNS." (PMID 33653409, 2021).
migraine (continued). "Therefore, our hypothesis was that overexpression of miR‐34a‐5p may inhibit the expression of SIRT1 and up‐regulation of IL‐1β/COX2/PEG2, thereby triggering the release of CGRP to induce the pain during migraine." (PMID 33155431, 2021). "Although the treatment approaches for migraine are not yet well established, IL-1 receptor antagonists suppress migraine attacks in patients with the cryopyrin-associated periodic syndrome, where mutations in the inflammasome component NLRP3 result in over secretion of IL-1β." (PMID 37176049, 2023). "Thus, we predict that TRPA1-mediated SFKs activation may promote IL-1β protein expression, which, together with the increased CGRP release observed in this study, forms synergistic effects on TVS sensitization to enhance migraine pain transmission." (PMID 34830154, 2021). "Furthermore, the authors found that NLRP3 and IL-1β expression was significantly upregulated in the microglia of trigeminal nucleus caudalis (TNC), a place that receives and integrates pain signals from the trigeminal area and is considered as a central area relevant for migraine." (PMID 33785039, 2021). "In addition, the lack of correlation between age and IL-1β plasma levels, regardless of the important role of aging in the immune response, suggests that genetic or epigenetic factors are needed to develop MD in patients with migraine." (PMID 34575163, 2021). "Although gut microbiota profiles differed significantly between M + G and M + noG patients, plasma levels of migraine markers (CGRP and PGE2) and inflammatory indices (IL-1β, IL-6, NF-κB, TNF-α) did not." (PMID 41454664, 2026). "Another study demonstrated that IL-1β antagonist, MCP-1, and TGF-b1 were significantly increased in the CSF of patients with episodic tension-type headache (TTH) and migraine with and without aura compared to those without pain." (PMID 37176049, 2023). "A 2021 study measured cytokine levels in the blood in migraine patients and healthy controls and discovered that TNF-α was elevated, but IL1-β was not compared to controls." (PMID 35432179, 2022). "Significantly increased ictal IL-1β, IL-6 and TNF-α serum concentrations were measured in migraine patients with/without aura compared to post-ictal (after 1 week treatment) and healthy subjects not clearly indicative for a predictive value." (PMID 30795781, 2019). "As PKA activation promotes CGRP release but not increases in IL-1β gene expression, we therefore propose that PKA may direct SFKs to mediate CGRP release but not IL-1β gene expression downstream TRPA1 in migraine." (PMID 34830154, 2021). "Therefore, we measured the levels of IL-1β, CCL3, CCL4, CXCL1, CCL22, and CCL18 in a cohort of 83 patients with MD, which included 44 EOMD and 39 LOMD, and 64 patients with migraine without vestibular symptoms to control the effect of migraine itself on cytokine levels." (PMID 34575163, 2021).